SP110 (SP110 nuclear body protein)
Description:
Transcription factor. May be a nuclear hormone receptor coactivator. Enhances transcription of genes with retinoic acid response elements (RARE).
Synonyms: IFI41; IFI75; IPR1; VODI
Tractability: PROTAC: ubiquitination databases record sites on it; its protein half-life has been measured.
Gene: Protein-coding gene on chromosome 2 (230,165,186 to 230,225,729, reverse strand). Ensembl gene ENSG00000135899.
Subcellular location: Nucleus
Subcellular location (Human Protein Atlas): Nucleoplasm
Gene Ontology:
Molecular function: DNA binding; DNA-binding transcription factor activity, RNA polymerase II-specific
Biological process: regulation of transcription by RNA polymerase II
Cellular component: nucleoplasm; nucleus
Genetic constraint (gnomAD): Loss-of-function variants: 34 observed, 54.78 expected, observed/expected ratio (o/e) 0.62, 90% interval 0.47 to 0.83. The upper end of that interval is the gene's LOEUF score, 0.83, which puts it in group 3 of 6, group 1 being the genes least tolerant of losing a copy. Missense variants: 554 observed, 666.09 expected, observed/expected ratio (o/e) 0.83, 90% interval 0.77 to 0.89. Synonymous variants: 211 observed, 244.08 expected, observed/expected ratio (o/e) 0.86, 90% interval 0.77 to 0.97.
Gene-disease validity (ClinGen):
ClinGen rates the evidence that SP110 causes each of these diseases.
hepatic veno-occlusive disease-immunodeficiency syndrome (autosomal recessive): Definitive. Hepatic veno-occlusive disease-immunodeficiency syndrome is characterized by the association of severe hypogammaglobulinemia, combined T and B cell immunodeficiency, absent lymph node germinal centers, absent tissue plasma cells and hepatic veno-occlusive disease.
Homologues: Orthologues: chimpanzee SP110 (98% identical), macaque SP110 (62% identical), dog SP110 (58% identical), pig SP110 (53% identical), rat Sp110 (33% identical), mouse Sp110 (32% identical), Caenorhabditis elegans hmg-3 (7% identical), Caenorhabditis elegans hmg-4 (6% identical). Paralogues in human: SP140 (34% identical), SP100 (34% identical), SP140L (30% identical), UBTF (9% identical), TOX4 (8% identical), SSRP1 (7% identical), TOX2 (7% identical), TOX3 (7% identical), HMGXB4 (6% identical), TOX (6% identical), SMARCE1 (6% identical), HMGB1 (5% identical), and 8 more.
Diseases named in the same sentence as SP110 in open-access papers:
SP110 is named in the same sentence as 48 diseases in open-access papers, as found by Europe PMC text mining. Sharing a sentence is not in itself a finding about the gene and the disease. The quoted sentences say what the papers report.
tuberculosis (16 papers, 2010 to 2025). A chronic, recurrent infection caused by the bacterium Mycobacterium tuberculosis. "A number of genetic variants of SP110 have been reported to be associated with susceptibility to human tuberculosis, although the results of studies regarding the relationship between SP110 polymorphisms and TB susceptibility are inconsistent." (PMID 29642903, 2018). "Recent studies focusing on the association of SP110 gene polymorphisms with tuberculosis susceptibility." (PMID 28969051, 2017). "On the contrary, a previous study has reported an association of Sp110 polymorphisms with susceptibility to tuberculosis in West Africa." (PMID 20718957, 2010). "Moreover, polymorphisms of the human homologue of the mouse Ipr1 gene (Sp110) are associated with tuberculosis susceptibility." (PMID 27622275, 2016). "Recent studies found that Sp110 polymorphisms are linked to tuberculosis susceptibility." (PMID 27622275, 2016). "Studies conducted so far, support the idea that intracellular factors like Coronin-1, Sp110 and TLRs play a decisive role in the progression of TB infection, at least in experimental tuberculosis." (PMID 20718957, 2010). "Our data suggest that Coronin-1, Sp110 and at least Toll-like receptor-2 molecules are involved in the infectious process of tuberculosis." (PMID 20718957, 2010). "In this study, we observed an increased expression of TLR-2, Coronin-1, and Sp110 mRNA levels in PBMCs of patients with tuberculosis and in close contacts of patients that had latent tuberculosis infection." (PMID 20718957, 2010). "Attempts to apply this knowledge to human tuberculosis have shown that SP110, the homolog of ipr1, could be a good marker of susceptibility but only for some populations." (PMID 36678397, 2022). "The closest human homologue to Ipr1 is Sp110, and mutations in Sp110 have been associated with hepatic veno-occlusive disease with immunodeficiency (VODI); however, the role of Sp110 in human tuberculosis is still being debated." (PMID 24009502, 2013). "We determined that the tuberculosis susceptibility allele was located within the HSR repeat region, which encodes multiple copies of Ifi75 (interferon-inducible 75) gene (human homologue is known as Sp110)." (PMID 24009502, 2013). "The mRNA expression of Coronin-1, Sp110 and TLR-2 was significantly higher in patients with active tuberculosis and subjects with latent disease compared to the uninfected ones." (PMID 20718957, 2010). "In conclusion, in the present work we have shown that mRNA levels of Coronin-1, Sp110 and TLR-2 are increased in patients with tuberculosis and in close contacts of patients with latent tuberculosis infection." (PMID 20718957, 2010).
Immunodeficiency (10 papers, 2013 to 2025). Failure of the immune system to protect the body adequately from infection, due to the absence or insufficiency of some component process or substance. "When SP110 is disrupted, it can lead to serious immune deficiencies, highlighting just how vital it is to the immune system’s balance and function." (PMID 41188771, 2025). "Loss-of-function mutations in SP110 are associated with the veno-occulusive disease with immunodeficiency (25, –, 27)." (PMID 39162523, 2024). "Mutations in the SP110 gene result in venoocclusive disease with immunodeficiency; this disease is an autosomal recessive disorder of severe combined T and B cell immunodeficiency with absent lymph node germinal centers." (PMID 26347895, 2015). "Furthermore, SP110 mutations associate with hepatic venoocclusive disease with immunodeficiency, a rare form of severe combined immune deficiency." (PMID 38113079, 2023). "Furthermore, mutations in the Sp110 gene have been associated with immunodeficiency diseases, such as viral hepatitis infection and hepatitis C virus infection-induced chronic liver diseases." (PMID 27622275, 2016). "MHC Class II defect and defects in STIM1, DOCK2, SP110, ZAP70, and STK4 genes are categorized as combined immunodeficiencies as per the 2019 International Union of Immunological Societies Expert Committee classification of human inborn errors of immunity (IEI)." (PMID 33628209, 2020).
pulmonary TB (8 papers, 2010 to 2024). "Individuals with the CT and TT genotypes of rs722555 in SP110 have an increased risk of pulmonary TB." (PMID 36249417, 2022). "The results in this report demonstrate that the rs722555 SNP in the SP110 gene is a risk factor for pulmonary TB susceptibility in the Mongolian population in China." (PMID 36249417, 2022). "In summary, this study has found six tag SNPs for SP110 associated with all forms of TB and one SNP associated with extra-pulmonary TB." (PMID 25006821, 2014). "To understand if the population diversity and genetic heredity could influence the association of SNPs in ASAP1 and SP110 with the susceptibility of TB, we selected a set of SNPs and focused on genetic polymorphisms relating to pulmonary TB in a minority Mongolian population in China." (PMID 36249417, 2022). "The genotypic distributions of rs113579, rs9061, rs722555, rs3948464, rs11679983, rs1365576, and rs11556887 in SP110 were also in accordance with the HWE among the pulmonary TB patients and healthy controls." (PMID 36249417, 2022). "Similar theme was seen for SP110 gene for which we have previously identified a risk for rs1427294 of in LNTB but not pulmonary TB." (PMID 36672948, 2023). "The mouse homolog of this gene, Ipr1, was previously shown to mediate innate immunity in sst1 congenic mice and SP110 variants were associated in some settings with human pulmonary TB, but not others." (PMID 30319657, 2018). "The findings support a role for SP110 in both pulmonary TB and extra-pulmonary TB." (PMID 25006821, 2014). "Thus, the role and function of Sp110 in human pulmonary tuberculosis needs further investigation." (PMID 20718957, 2010).
breast cancer (4 papers, 2020 to 2025). A primary or metastatic malignant neoplasm involving the breast. "While SP100 acts as a tumor suppressor in malignancies like breast cancer, SP110 and SP140 are implicated in promoting oral squamous cell carcinoma and glioma progression, respectively, and SP140L is linked to poor prognosis in pancreatic adenocarcinoma." (PMID 41188771, 2025). "A search of relevant literature in the past decade found that SP110 is a special transcription factor of tumor involved in the carcinogenic regulation of breast cancer and ovarian cancer." (PMID 37396042, 2023). "SP110 was reported as a commonly deregulated gene in mammary cancer and an early inducement in melanoma and nonmelanoma skin cancer." (PMID 33098370, 2020).
pneumonia (4 papers, 2023 to 2025). An acute, acute and chronic, or chronic inflammation focally or diffusely affecting the lung parenchyma, caused by an infection in one or both of the lungs (by bacteria, viruses, fungi, or mycoplasma.). "In Baladi goats with pneumonia and healthy control group, PCR-DNA sequencing revealed SNPs linked to pneumonia susceptibility and resistance in immunological genes (SLC11A1, CD-14, CCL2, TLR1, TLR7, TLR8, TLR9, defensin, SP110, SPP1, BP1, A2M, ADORA3, CARD15, IRF3, and SCART1)." (PMID 40221769, 2025). "The immune genes’ mRNA levels in goats (SLC11A1, CD-14, CCL2, TLR1, TLR7, TLR8, TLR9, defensin, SP110, SPP1, BP1, A2M, ADORA3, CARD15, IRF3, and SCART1) varied between the healthy and infected goats with pneumonia." (PMID 40711280, 2025). "Through PCR-DNA sequencing in Baladi goats with and without pneumonia, SNPs linked to pneumonia susceptibility and resistance were discovered in the immunological (SLC11A1, CD-14, CCL2, TLR1, TLR7, TLR8, TLR9, defensin, SP110, SPP1, BP1, A2M, ADORA3, CARD15, IRF3, and SCART1) genes." (PMID 40711280, 2025). "The levels of immunological genes (SLC11A1, CD-14, CCL2, TLR1, TLR7, TLR8, TLR9, defensin, SP110, SPP1, BP1, A2M, ADORA3, CARD15, IRF3, and SCART1) vary in goats with and without pneumonia." (PMID 40221769, 2025). "Real-time PCR was conducted to quantify the expression levels of immunological markers (SLC11A1, CD-14, CCL2, TLR1, TLR7, TLR8, TLR9, β defensin, SP110, SPP1, BP1, A2M, ADORA3, CARD15, IRF3, and SCART1) in Baladi goats with and without pneumonia resistance." (PMID 36977224, 2023).
viral infections (3 papers, 2013 to 2025). "The SP110 protein, also known as Ipr1, is an interferon-inducible protein that plays a role in the innate immune response to viral infections." (PMID 41012626, 2025). "During viral infections in humans, SP110 has been shown to interact with the Remodelling and Spacing Factor 1 (RSF1) and Activating Transcription Factor 7 Interacting Protein (ATF7IP), suggesting it is involved in chromatin remodelling." (PMID 30082726, 2018). "Recently cellular proteins have been described that mediate the interaction of SP110 and viral proteins during viral infections." (PMID 24069471, 2013).
osteosarcoma (2 papers, 2024 to 2025). A usually aggressive malignant bone-forming mesenchymal neoplasm, predominantly affecting adolescents and young adults. "Although the roles of SP110, HHAT, MORC4, PAGE5, MAP7, and CAMK1G in osteosarcoma have rarely been reported, their involvement in other types of cancer has been revealed." (PMID 39980969, 2024).
pancreatic adenocarcinoma (2 papers, 2023 to 2025). "It was found that RTP4, SERTAD2, and SP110 were significantly expressed in all pancreatic cancer cells, including those of pancreatic ductal carcinoma, pancreatic adenocarcinoma and metastatic carcinoma, providing a reliable basis for subsequent elucidation of pancreatic cancer pathogenesis." (PMID 37396042, 2023).
pancreatic cancer (2 papers, 2023). "We also found that pancreatic cancer patients with elevated expression of MAPK1, LRRFIP1, SP110, and NFE2 had a decreased rate of survival relative to patients with lower expression of these genes." (PMID 37627195, 2023).
atopic dermatitis (1 paper, 2025). "Of interest, coding variants in SP110 are associated with atopic dermatitis and SP110 is part of the epidermal anti-viral response." (PMID 40998781, 2025).
endometriosis (1 paper, 2025). The growth of functional endometrial tissue in anatomic sites outside the uterine body. "Collectively, PMP22, QSOX1, REV3L, SP110 may serve as potential diagnostic biomarkers for early diagnosis and targeted therapy of endometriosis and SLE." (PMID 39744159, 2025). "Four co-diagnostic genes (PMP22, QSOX1, REV3L, SP110) were identified for endometriosis and SLE." (PMID 39744159, 2025). "Subsequently, by LASSO regression analysis, we constructed prediction models for 15 diagnostic genes in the endometriosis cohort and 6 diagnostic genes in the SLE cohort, respectively, and identified four co-diagnostic genes (PMP22, QSOX1, REV3L, SP110)." (PMID 39744159, 2025). "The expression of PMP22, QSOX1 and SP110 were significantly higher in the ovarian endometriotic tissues from endometriosis patients compared to normal endometrial." (PMID 39744159, 2025). "Subsequently, by the intersection analysis, we obtained four overlapping genes (PMP22, QSOX1, REV3L, SP110) as potential co-diagnostic genes for SLE and endometriosis." (PMID 39744159, 2025). "The expression of four potential co-diagnostic genes in the endometriosis validation cohort (GSE31515 and GSE87909) showed that the expression of QSOX1 and SP110 were significantly upregulated in the endometriosis group than normal group, which were consistent with the training group." (PMID 39744159, 2025). "We found that SP110 was significantly upregulated in endometriosis patients and SLE patients, which may be related to the aberrant immune infiltration." (PMID 39744159, 2025).
glioma (1 paper, 2025). A benign or malignant brain and spinal cord tumor that arises from glial cells (astrocytes, oligodendrocytes, ependymal cells). "SP110 was evaluated in 7 studies involving various cancers: DLBCL, PAAD, oral cancer, lung adenocarcinoma, glioma, and ccRCC." (PMID 41188771, 2025).
hepatocellular carcinoma (1 paper, 2024). A malignant tumor that arises from hepatocytes. "In hepatitis B virus-induced hepatocellular carcinoma, high SP110 expression was correlated with a shorter survival rate among patients." (PMID 39980969, 2024).
Hypercholesterolemia (1 paper, 2013). An increased concentration of cholesterol in the blood. "Of the DEGs in the MCA that were up-regulated in the hypertension plus hypercholesterolemia group vs. sham controls on a normal diet, EPHA1 had the largest fold change, followed by SP110, and SLFN14." (PMID 23874591, 2013). "Among the highly up-regulated genes in the MCA of the hypertension plus hypercholesterolemia group compared to sham controls were EPHA1, SP110, SLFN14." (PMID 23874591, 2013).
latent infection (1 paper, 2010). "In contrast, expression of Coronin-1, Sp110 and TLR-2 mRNAs were not significantly different between the patients (group A) and the close contacts with latent infection (group B)." (PMID 20718957, 2010).
leukemia (1 paper, 2025). A malignant (clonal) hematologic disorder, involving hematopoietic stem cells and characterized by the presence of primitive or atypical myeloid or lymphoid cells in the bone marrow and the blood. "Regarding B cells, ATLL IgG strongly recognized proteins like SP110 and SP100, which are linked to B cell survival, NCOA3, associated with leukemia development, and BCAS4, related to cancer progression." (PMID 41303346, 2025).
lung adenocarcinoma (1 paper, 2025). A carcinoma that arises from the lung and is characterized by the presence of malignant glandular epithelial cells. "In PAAD, high expression of SP110 was correlated with a better prognosis, while in lung adenocarcinoma and OSCC, it was associated with a poor prognosis." (PMID 41188771, 2025). "High SP110 expression was consistently associated with poor prognosis in oral cancer, lung adenocarcinoma, PAAD, and ccRCC." (PMID 41188771, 2025).
lymphoma (1 paper, 2021). A malignant (clonal) proliferation of B- lymphocytes or T- lymphocytes which involves the lymph nodes, bone marrow and/or extranodal sites. "Additionally, 18% of lymphoma cell lines are significant for SP110 depletion, which may reveal a population of lymphoma subtypes that are vulnerable to prospective SP110 inhibitors." (PMID 34298819, 2021).
oral squamous cell carcinoma (1 paper, 2025). "Another member, SP110, is significantly overexpressed in oral squamous cell carcinoma (OSCC)." (PMID 41188771, 2025).
promyelocytic leukemia (1 paper, 2024). "SP110 was initially identified within PML (promyelocytic leukemia) nuclear bodies, which are multiprotein complexes located within the nucleus and involved in regulating various nuclear functions such as DNA replication, gene transcription, and epigenetic inheritance." (PMID 38891697, 2024).
pulmonary disease (1 paper, 2014). "This is the first study to show an association between SP110 variants and both extrapulmonary and pulmonary disease, and the first published study of SP110 in the Vietnamese." (PMID 25006821, 2014).
renal carcinoma (1 paper, 2025). A carcinoma arising from the epithelium of the renal parenchyma or the renal pelvis. "SP110 overexpression was tied to poor prognosis in oral, lung, and renal cancers but was protective in DLBCL." (PMID 41188771, 2025).
tendinitis (1 paper, 2024). Inflammation of a tendon, usually resulting from an overuse injury. "The identification of key transcription factors, such as SP110 and CREB5, involved in the regulation of inflammasome genes, provides new insights into the transcriptional control mechanisms in tendinitis." (PMID 38919626, 2024). "Transcription factors like SP110 and CREB5 emerged as key regulators of inflammasome genes, providing insight into the transcriptional control mechanisms in tendinitis." (PMID 38919626, 2024).
type 2 diabetes (1 paper, 2015). "Specifically, IRF7 and NLRC5 are associated with type 2 diabetes, and SP110 and ZBP1 are associated with waist circumference and body fat distribution, respectively." (PMID 25868721, 2015).